IL1B (interleukin 1 beta)
Diseases named in the same sentence as IL1B in open-access papers (continued):
Sharing a sentence is not in itself a finding about the gene and the disease.
chronic hepatitis C (11 papers, 2012 to 2024). "A growing body of evidence has suggested that proinflammatory cytokines (IL-1β and IL-18) play a substantial role in both acute and chronic hepatitis C." (PMID 30728751, 2019). "In this report we reveal a linkage of hepatic inflammation and disease in chronic hepatitis C patients attributed to IL-1β production by liver macrophages." (PMID 23633957, 2013). "Immunohistochemical analysis of healthy control and chronic hepatitis C liver sections revealed that Kupffer cells, resident hepatic macrophages, are the primary cellular source of hepatic IL-1β during HCV infection." (PMID 23633957, 2013). "However, the expression of IL-1β (mRNA levels) in the liver biopsies of chronic hepatitis C patients was found to be comparable to the controls." (PMID 30728751, 2019). "To assess whether circulating IL-1β can be detected during chronic HCV infection, we evaluated serum levels of IL-1β from both chronic hepatitis C patients and healthy controls." (PMID 23633957, 2013). "Chronic hepatitis C patients exhibited elevated levels of serum IL-1β compared to healthy controls." (PMID 23633957, 2013). "RNA sequencing analysis comparing THP1 cells and chronic hepatitis C patient liver demonstrates that viral engagement of the NLRP3 inflammasome stimulates IL-1β production to drive proinflammatory cytokine, chemokine, and immune-regulatory gene expression networks linked with HCV disease severity." (PMID 23633957, 2013). "We found that serum IL-1β levels are elevated in chronic hepatitis C patients." (PMID 23633957, 2013). "And Gramantieri reported that an imbalance between IL-1β and IL-1Ra at the tissue level may contribute to the pathogenesis and activation of chronic hepatitis C." (PMID 22844472, 2012). "It is also documented that liver-infiltrating T cells from chronic hepatitis C patients produced IFN(interferon)-γ, apoptotic hepatocytes released IL-1α, and macrophages exposed to HCV secreted IL-1β and IL-18." (PMID 36901973, 2023). "It is also documented that liver-infiltrating T cells from chronic hepatitis C patients produce IFN-γ, apoptotic hepatocytes release IL-1α, and macrophages exposed to HCV induce IL-1β and IL-18 secretion." (PMID 35887291, 2022). "Whereas, other authors used mononuclear cells from patients with chronic hepatitis C to assess the effects of E2 and P4 on the production of TNF-α, IL-1β, IL-8, and macrophage chemotactic protein (MCP)-1." (PMID 31546715, 2019). "In chronic hepatitis C, the release of TNF-α and IL-1β by circulating mononuclear cells is greater than in healthy individuals." (PMID 31546715, 2019). "This is an important finding since some studies have shown that the largest proportion of cellular infiltrate found in a liver with chronic hepatitis C is TH1 cells, such as IL-1b, IL-2, IL-6, IL-8, TNF-α and IFN." (PMID 22830036, 2012). "Infection with HCV, in both cultured cells and patients, activates the NLRP3 inflammasome of macrophages and the production of IL-1β and other cytokines which may be the mechanism driving the higher incidence of CHD in patients with chronic hepatitis C." (PMID 25438910, 2014). "We found that while CD68-negative cell populations, including hepatocytes, contained little or no IL-1β, liver macrophages from chronic hepatitis C patients expressed IL-1β, and CD68-positive cells were present at increased frequency compared with healthy controls." (PMID 23633957, 2013). "Indeed, accumulating evidence showed an increase in proinflammatory mediators, principally IL-6, IL-1β, interferon-γ (IFN-γ), and TNF-α in depressed individuals and in patients developing depressive symptoms after therapeutic treatments, such as IFN-α therapy for chronic hepatitis C." (PMID 35886944, 2022).
colorectal adenocarcinoma (11 papers, 2016 to 2025). The most common type of colorectal carcinoma. "The expression levels of four inflammation-related genes (TRPV1, iNOS, IL-1β, and IL-8) were decreased significantly (p < 0.05) in the human colorectal adenocarcinoma Caco-2 cells treated with three different concentrations (12.5, 25, and 50 mg/L) of PS-MPs for 24 and 48 h." (PMID 34809705, 2021). "We also interrogated the co-expression of the reported genes on the same data set (17157 genes from 244 colorectal adenocarcinoma cases); strikingly, IL1B, IL8 and CXCL1 display the highest correlation with IL1A, with a Pearson correlation of 0.66, 0.55 and 0.51 respectively." (PMID 27708224, 2016). "F. nucleatum induces IL-8, IL-1β, TNF-α, and ROS generation in Caco-2 colorectal adenocarcinoma cells by impairing autophagic flux." (PMID 31737164, 2019). "Similar anti-inflammatory effects of the fungal metabolites were observed in the human colorectal adenocarcinoma cell line DLD-1 after stimulation with IFN-γ (10 ng/ml), TNF-α (10 ng/ml), and IL-1β (5 ng/ml)." (PMID 28824460, 2017). "In addition, higher HLA‐DRA or IL1B expression levels also predicted good overall survival in kidney renal clear cell carcinoma (KIRC) and colorectal adenocarcinoma (COAD), respectively." (PMID 38483933, 2024). "Despite showing no cytotoxicity against human colorectal adenocarcinoma (HT-29), basil polyphenolic extract decreases the pro-inflammatory cytokine IL-1β in a neoplastic environment, indicating its potential role in cancer prevention." (PMID 39519685, 2024). "Thus, the expression of IL-1β and TNF-α could be largely suppressed in colorectal adenocarcinoma in mice by treatment with a combination of zotarolimus and 5-FU." (PMID 34361836, 2021).
coronary atherosclerosis (11 papers, 2013 to 2025). Atherosclerosis of the coronary vasculature. "NETs produced by neutrophils have been shown to enhance local inflammation, inducing ROS release, SMCs lysis and IL-1β production by macrophages, as well as thrombotic and haemorrhagic complications of coronary atherosclerosis." (PMID 33086507, 2020). "In the pathogenesis of coronary atherosclerosis, local macrophage-driven inflammation and secretion of proinflammatory cytokines, interleukin-1β (IL-1β) in particular, are recognized as key factors." (PMID 24244322, 2013). "Clinical evidence showed that the patients with coronary atherosclerosis had lower Map1lc3 expression in peripheral leukocytes, and autophagy gene defect in macrophages led to excessive activation of inflammasomes and overexpression of IL-1β." (PMID 40090940, 2025). "There are no available reports on the possible connection between IL-1B and IL-1RN polymorphisms and the accelerated progression of coronary atherosclerosis." (PMID 33801199, 2021). "It has also been reported that pericardial concentrations of IL-1β may reflect the extent of ischaemic heart disease and that elevated IL-1β concentrations in pericardial fluid may also directly promote the process of coronary atherosclerosis." (PMID 27805242, 2016). "IL-1β and NLRP3 have been positively correlated with the extent of coronary atherosclerosis as assessed by SYNTAX score and CLINICAL SYNTAX score, while NLRP3 has also been positively correlated with the GENSINI score and lesion characteristics of coronary syndrome patients." (PMID 34685553, 2021).
cutaneous melanoma (11 papers, 2017 to 2025). A primary melanoma arising from atypical melanocytes in the skin. "In cutaneous melanoma, melphalan treatment was associated with enhanced expression of the pro-inflammatory cytokines: IL-1β, IL-8, and IL-6 and was found to induce apoptosis through ER stress and reactive oxygen species." (PMID 41160198, 2025). "Current available data suggest that TNF-α and interleukins IL1B, IL-6, IL-8 and IL-18 can modulate the proliferation, survival and migration of cutaneous melanoma cells." (PMID 37047539, 2023). "Most skin melanoma cell lines express low levels of IL‐1β, with only few exceptions, particularly the cell line 1205Lu." (PMID 36707938, 2023). "Analyses of the Cancer Genome Atlas (TCGA) and the GTEx datasets exhibited highly significant increases in NLRP3 and IL-1β expression in cutaneous melanoma samples compared to normal skin." (PMID 33649199, 2021). "A similar pattern is observed with IL1B, which has crucial protective roles in KIRC and BRCA while being associated with significantly higher risks for stomach adenocarcinoma (STAD) and skin cutaneous melanoma (SKCM), despite its complex involvement in inflammatory pathways within tumors." (PMID 39635438, 2024). "In skin cutaneous melanoma (SKCM), cancers with high expression of IL1B, CCL5, CXCL10, and TNFSF15 exhibited better prognoses." (PMID 37980406, 2023). "Analysis of cancer genome datasets (TCGA and GTEx) revealed greater NLRP3 and IL-1β expression in cutaneous melanoma samples (n = 469) compared to normal skin (n = 324), with a highly significant correlation between NLRP3 and IL-1β (P < 0.0001)." (PMID 33649199, 2021). "In humans, analyses of the TCGA dataset revealed positive mRNA correlations from cutaneous melanoma biopsies for expression of NLRP3 and IL‐6 (p=4.86e-20), IL‐6 and the STAT3 target gene Socs3 (p=1.82e-62), IL-1β and Socs3 (p=1.71e-31)." (PMID 34531850, 2021). "More recent findings emphasize the key role of nucleotide‐binding domain, leucine‐rich containing family, pyrin domain‐containing‐3 (NLRP3)/IL‐1β signaling in inducing the expansion of PMN‐MDSCs and subsequent suppression of anti‐tumor immunity in cutaneous melanoma." (PMID 38775220, 2024).
dilated cardiomyopathy (11 papers, 2015 to 2025). Cardiomyopathy which is characterized by dilation and contractile dysfunction of the left and right ventricles. "The pathways involved in amoebiasis, cytokine‒cytokine receptor interaction and dilated cardiomyopathy involve several genes, such as Tgfb2 and Il1b, which are related to TGFβ signaling and NFκB signaling." (PMID 40474744, 2025). "Elevated levels of IL-6 and IL-1β in individuals with dilated cardiomyopathy (DCM) can lead to cardiomyocyte apoptosis and impaired systolic function of the heart." (PMID 37512058, 2023). "In support of this, high levels of plasma IFNγ, TNFα, (IL-1β), and IL-6 correlated with the severity of dilated cardiomyopathy in chagasic patients, indicating that exacerbated immune can cause local damage." (PMID 29867974, 2018). "IFNγ protected against the development of severe chronic myocarditis, pericarditis, and dilated cardiomyopathy after infection with Coxsackievirus B3, reducing mast cell degranulation, volume of fibrous myocardial tissue and production of profibrotic cytokines such as TGFb, IL-1b and IL-4." (PMID 36674665, 2023).
enteropathy (11 papers, 2016 to 2025). "A recent study suggested that NLRP3 inflammasome activation and associated IL-1β release play a key role in NSAID-induced enteropathy." (PMID 30555323, 2018). "Numerous cytokines that circulate at very low concentrations were not able to be quantified in the cohort and several of these (amylin, glucagon, interferon-γ, IL-1B, IL-17A) have direct associations with MetS, which may undercut the argument for enteropathy as an etiology for MetS." (PMID 36096405, 2022). "The observed mucosal barrier changes were similar to previous reports on AOM/DSS-induced enteropathy, mainly featured by losing the expression of ZO-1 and occluding and blooming release of inflammatory factors, IL-1β and -IL6." (PMID 37200915, 2023). "NLRP3 inflammasome-derived IL-1β played a crucial role in NSAID-induced enteropathy." (PMID 35222032, 2022). "Resolvin D1, a pro-resolving lipid mediator, could ameliorate NSAID-associated enteropathy by inhibiting the expression of TNF-α and IL-1β via inhibition of related signaling pathways." (PMID 35222032, 2022). "Administration of p31-43, but not scrambled or inverted peptides, to normal mice induced enteropathy in the proximal small intestine, associated with increased production of type I interferon and mature IL-1β." (PMID 30761127, 2019). "We previously reported that P31-43 induces additional pro-inflammatory effects on Caco-2 cells, namely NLRP3 inflammasome activation and NF-κB p65 translocation into the nucleus with consequent increased IL-1β production and upregulation of IL-15, a known mediator of the gliadin-induced enteropathy." (PMID 30981209, 2019). "Consistent with our previous results, a rat model of diclofenac-induced enteropathy revealed that S. boulardii CNCM I-745 prevented TLR2/4, MYD88, and NF-κB p65 overexpression, thereby decreasing proinflammatory cytokines, such as IL-1β." (PMID 40872558, 2025). "We also analyzed the mRNA expression change of IL-1β, one of the inflammatory cytokines involved in NSAID-induced enteropathy." (PMID 32443501, 2020).
glomerulosclerosis (11 papers, 2018 to 2025). A hardening of the kidney glomerulus caused by scarring of the blood vessels. "DAF deficiency promotes FSGS-like glomerulosclerosis through complement activation and IL-1β-driven inflammation." (PMID 41009556, 2025). "When renal function is impaired, the glomerular mesangial cells produce a large amount of interleukin-6 (IL-6), interleukin-1β (IL-1β), and other inflammatory mediators, exacerbating glomerulosclerosis and renal function decline." (PMID 36615439, 2022). "IL-1β, as an autocrine growth factor, has been demonstrated to be involved in inducing the proliferation of mesangial cells, which leads to glomerulosclerosis." (PMID 33688363, 2021). "This disruption promotes lipid accumulation and macrophage foam cell formation, leading to the sustained release of pro-inflammatory cytokines such as TNF-α, IL-1β, and MCP-1, which accelerate glomerulosclerosis and tubulointerstitial fibrosis." (PMID 41282283, 2025). "We observed that several components of SASP known to play a potential role in glomerulosclerosis, such as PAI‐1, IL‐1β, IL‐6, or MMP13, were upregulated in kidneys of old mice as compared to young mice." (PMID 34725920, 2021). "TWG alleviates glomerulosclerosis by exerting antimicroinflammatory effects, including reducing macrophage infiltration in the glomeruli, suppressing TNF-α, IL-1β and TGF-β1 overexpression in the kidney and inhibiting p38 MAPK and NF-κB signaling activities." (PMID 30021637, 2018). "During glomerulosclerosis resident cells secrete pro-inflammatory factors such as tumor necrosis factor alpha (TNF-α), interleukin 1 beta (IL-1β), and transforming growth factor beta (TGF-β) which promote ECM synthesis and myofibroblast accumulation in the glomerulus." (PMID 32340145, 2020).
kidney injury (11 papers, 2015 to 2024). Trauma to the kidney. "IL-1β is also a key mediator of the inflammatory response, and has been associated with kidney injury." (PMID 39055309, 2023). "Calcium flux, mitochondrial damage, and mitophagy dysfunction observed in cisplatin-induced kidney injury have been implicated in the NFκB and NLRP3 inflammasome pathway-mediated release of the pro-inflammatory cytokine IL-1β." (PMID 39169052, 2024). "In particular, TNF-α, IL-1β, and IL-6 play a key role in cisplatin-induced kidney injury." (PMID 32089779, 2020). "The underlying mechanism study showed that NF-κB activation triggers the release of inflammatory cytokines such as interleukin-1beta (IL-1β), interleukin-6 (IL-6) and tumor necrosis factor alpha (TNF-α) that exacerbating kidney injury (Place and Kanneganti., 2018)." (PMID 36278223, 2022). "Similarly, FN exhibited dose-dependent anti-inflammatory action via suppressing the pro-inflammatory mediators, involving IL-1β and TNF-α, as part of its renal protective mechanism against MTX-induced kidney injury." (PMID 35712704, 2022).
Lewis lung carcinoma (11 papers, 2006 to 2025). "IL-1b, a proinflammatory cytokine, was proposed as a potential angiogenic factor in Lewis lung carcinoma." (PMID 36499629, 2022). "While in Lewis lung carcinoma, IL-1β drives tumor growth through its upregulation of VEGF and the proangiogenic chemokine (C-X-C motif) ligand 2 (CXCL2)." (PMID 31293586, 2019). "An experimental model with murine Lewis lung carcinoma cells transduced with a retroviral vector expressing IL-1β, showed that cells infected with human IL-1β expressing vector grew rapidly in mice despite the lack of a difference in the cell growth in vitro." (PMID 28927416, 2017). "Moreover, FLP also reduces serum TNF-α, IL-1β, and IL-6 level in a Lewis lung carcinoma xenograft mouse." (PMID 26597177, 2015). "For example, in Lewis lung carcinoma in addition to IL-1 receptor induction of proangiogenic chemokine CXCL2 driving tumor promoting angiogenesis, IL-1β driven neovascularization was found to be dependent on infiltrating cyclooxgenase 2 (COX-2) positive macrophages." (PMID 31293586, 2019).
male infertility (11 papers, 2018 to 2025). The inability of the male to effect fertilization of an ovum after a specified period of unprotected intercourse. "Male infertility is well recognized to be brought on by the unchecked production of pro-inflammatory cytokines in the testes, such as IL-1b and TNF-a, which are damaging to spermatogenesis." (PMID 38500117, 2024). "This disruption is caused by the secretion of inflammatory factors, such as IL-6, IL-1β, TNFα, and I IFNs, which disrupt sperm formation and transport, ultimately resulting in male infertility." (PMID 38300431, 2024). "In this context, we discussed the NLRP3 inflammation, a multiprotein complex that initiates IL-1β–mediated inflammatory responses, and its relationship with male infertility." (PMID 37476898, 2023). "Sertoli cells have been shown to generate IL-1β via NLRP3 inflammasome activation, and NLRP3 activation has been linked to male infertility in both preclinical and clinical studies, providing a potential mechanistic pathway that connects SD to impaired sperm parameters in humans." (PMID 41154744, 2025). "IL-1β was released from TM to the testicular stroma, affecting adjacent Leydig cells, inhibiting testosterone synthesis and leading to impaired spermatogenesis and ultimately male infertility." (PMID 33193351, 2020). "The IL-1β is released from TM to the testicular interstitium where it affects adjacent Leydig cells and inhibits testosterone synthesis, leading to the impairment of spermatogenesis and, ultimately, male infertility." (PMID 31474981, 2019). "The results highlight IFN-γ, IL-1β, IL-6, LPO, 8-OHdG, and TAC evaluation in seminal plasma for a comprehensive state of male infertility to improve therapeutic intervention in male partners of infertile couples and to prevent infections or diseases." (PMID 34577786, 2021). "Moreover, active compounds from natural products in classical prescriptions have been shown to improve male infertility by modulating SASP markers, including IL-1β, IL-6, and TNF-α." (PMID 40552151, 2025). "Gossypol-induced male infertility markedly and significantly increased the levels of testicular TBARS, NO, TNF-α, ADAM-17, and interleukins (IL-1β, IL-6, and IL-18) while significantly decreasing the levels of both TIMP-3 and IL-12 compared with those of the control group." (PMID 29849861, 2018).